INS (insulin)
Diseases named in the same sentence as INS in open-access papers (continued):
Sharing a sentence is not in itself a finding about the gene and the disease.
diabetes (continued). "Latent autoimmune diabetes in adults (LADA) or slowly progressive insulin-dependent diabetes mellitus (SPIDDM) is a form of autoimmune diabetes characterized by autoimmune destruction of pancreatic beta cells, leading to deficient insulin secretion." (PMID 40226121, 2025). "It brings serious question marks about the effectiveness, safety, and indeed other advantages of insulin as against oral agents among patients with uncontrolled diabetes." (PMID 40959330, 2025). "There are various types of diabetes: Type 1 diabetes is an autoimmune disorder where the body’s immune system attacks and destroys the insulin-producing beta cells in the pancreas." (PMID 40416402, 2025). "Future studies are needed to evaluate the role of α-cells in insulin secretion and diabetes pathogenesis." (PMID 39860066, 2025). "The administration of insulin as a treatment for diabetes frequently leads to the formation of anti-insulin antibodies (IAs)." (PMID 40004193, 2025). "Clinical trials and animal studies have shown that intranasal insulin delivery improves memory performance and has significant neuroprotective effects related to diabetes." (PMID 40574087, 2025). "Factors such as advanced age, duration of diabetes mellitus > 10 years, insulin therapy and the presence of comorbidities, particularly hypertension, were strongly linked to poor glycemic control." (PMID 40078898, 2025). "Diabetes is a common metabolic disorder characterized by chronic hyperglycemia resulting from defects in insulin production or action." (PMID 40943103, 2025). "Generally, the Ch-InMLS can be applied as a valid and reliable instrument to measure insulin medication literacy amongst patients with diabetes mellitus (DM)." (PMID 40242444, 2025). "These cells can be transplanted as an effective source of insulin in diabetes patients if they can be protected against the host immune system." (PMID 40002796, 2025). "In support of a role in diabetes development, IL-1 inhibits insulin secretion in a time-dependent manner that is first apparent ∼5 to 8 h after cytokine addition, and complete following an 18 h incubation." (PMID 40147772, 2025). "Diabetes mellitus (DM) is a chronic metabolic disorder characterised by persistent hyperglycemia resulting from impaired insulin secretion, insulin action, or both." (PMID 41597373, 2025). "There is, however, limited availability of safety data with respect to these newer non-insulin-based diabetes medications from the perspective of fetal development." (PMID 39993530, 2025). "These in vitro observations in human and rodent islets, as well as clonal beta cells, have been validated in islets derived from animal models of impaired insulin secretion and diabetes, and in islets from human donors with T2D." (PMID 40710299, 2025). "MQC dysregulation induces a retrograde signaling program that impairs identity and maturity in insulin-sensitive tissues including pancreas, liver and adipose, yielding metabolic disorders and driving systemic IR and diabetes progression." (PMID 40866350, 2025). "The central themes explored in the ET addressed insulin therapy,glycemic monitoring, hyperglycemia, hypoglycemia, physical activity, nutrition,pathophysiology of diabetes, late complications, school and technologies fordiabetes." (PMID 39899746, 2025). "Patients with diabetes demonstrate significantly higher blood glucose levels and impaired insulin secretion or action." (PMID 41516077, 2025). "Most of the research has focussed on Type 2 Diabetes Mellitus (T2DM), the most common form, stimulated by hyperglycaemia, causing insufficient insulin secretion or insulin resistance." (PMID 40863620, 2025). "Its fiber content is also very high, which additionally helps with insulin sensitivity and weight control, both important aspects in diabetes management." (PMID 40861594, 2025).
diabetes (continued). "The comprehensive review of patient cases revealed that among individuals with previously uncontrolled diabetes who achieved improved A1c levels, the majority were utilizing insulin consistently throughout the pandemic." (PMID 40700264, 2025). "Current clinical guidelines for monogenic diabetes typically suggest insulin as the primary treatment for MODY6, based chiefly on observational data from cases with NEUROD1 coding region mutations." (PMID 41255541, 2025). "During the baseline period, 84% of cohort patients were prescribed oral diabetes medication, 33% were prescribed insulin, and 79% were prescribed statin medication." (PMID 40693585, 2025). "Glycemic control (HbA1c, diabetes medications), insulin sensitivity (Matsuda Index, Homeostasis Model of Insulin Sensitivity, oral minimal model), and secretion (C-peptide model)." (PMID 39911520, 2025). "Among patients with diabetes, insulin use conferred an additional 52% increase in hazard compared with non-insulin users (HR 1.52, 95% CI: 1.38 to 1.67; p<0.001)." (PMID 40967652, 2025). "Complementary mechanisms of action and add‐on glucose lowering effects of the association of basal insulin (BI) and GLP‐1RAs (modified and reproduced, with permission of the American Diabetes Association)." (PMID 40678871, 2025). "Diabetes mellitus (DM) is a predominant metabolic disorder characterized by chronic hyperglycemia resulting from defects in insulin secretion." (PMID 41441018, 2025). "Diabetes mellitus (DM) is commonly caused by insufficient insulin secretion and β-cell mass." (PMID 41473243, 2025). "Oxidative stress is a central contributor to the pathogenesis and progression of diabetes mellitus, particularly through its role in β-cell dysfunction, insulin resistance, and the development of diabetic complications." (PMID 41155632, 2025). "Compared with patients with ELP, patients with NELP were older and more likely to be female, have Hispanic ethnicity, have public insurance, use insulin, and have uncontrolled diabetes but less likely to see endocrinologists." (PMID 40526387, 2025). "The drugs that are currently used to treat diabetes can be classified as α-glucosidase inhibitors, sulfonylureas, biguanides, and glinides, as well as insulin." (PMID 41020857, 2025). "The role of the private sector, as well as the engagement with the government, emerges as essential also in ensuring equitable distribution and access to insulin and other diabetes medications included in the WHO essential medicines list." (PMID 41338627, 2025). "The longitudinal study, which comprised 110 women with diabetes and examined the influence of insulin initiation treatment on BMD, showed that individuals using insulin had a greater loss of BMD at the femoral neck than women who did not use insulin." (PMID 40725728, 2025). "The adoption of insulin pumps in diabetes management has seen a significant rise globally, offering promising advancements in glycemic control." (PMID 41146752, 2025). "The strong model performance on the chaotic dataset for both prediabetes and diabetes progression suggests that Model 5 effectively captures the glucose-insulin regulatory system across all disease states." (PMID 40568093, 2025). "Insulin resistance (IR), a hallmark of type 2 diabetes mellitus (T2DM), arises from impaired cellular responsiveness to insulin, disrupting glucose homeostasis and driving hyperglycemia." (PMID 40866350, 2025). "Sensor-augmented pumps (SAPs) and automated insulin delivery (AID) systems are innovative technologies for diabetes management." (PMID 41220554, 2025). "The higher sarcopenia prevalence in T2DM patients is consistent with the understanding that diabetes accelerates muscle deterioration due to impaired insulin signaling, increased inflammation, and oxidative stress." (PMID 40955268, 2025).
diabetes (continued). "Despite the advancements in diabetes technology aimed at improving glycaemic control, insulin pump usage remains particularly low in Italy, especially among adults." (PMID 41036118, 2025). "The American Diabetes Association guidelines and other clinical organizations recommend SMBG, especially for insulin-treated patients; however, its effectiveness for non-insulin-treated patients has been debated." (PMID 41567897, 2025). "The effects of low serum Mg levels on diabetes are explained by its role in mediating insulin secretion and impacting insulin signalling and resistance, with similar effects on prediabetes progression." (PMID 40632722, 2025). "Of the diabetic patients prescribed metformin, 27.0% exclusively used metformin, 66.2% used additional oral diabetes medication, and 37.8% relied on insulin next to their oral diabetes therapy." (PMID 39797377, 2025). "Studies indicate that this effect is likely more impactful in patients with poorly controlled diabetes or existing reduced insulin sensitivity." (PMID 40428894, 2025). "Diabetes was defined as treatment with oral hypoglycemic agents or insulin, previous clinical diagnosis of diabetes, glycated hemoglobin level ≥6.5%, or nonfasting blood glucose level ≥200 mg/dL." (PMID 41466800, 2025). "Diabetes is defined by elevated levels of glucose in the blood, compromised tolerance toglucose, impaired secretion of insulin, and resistance to insulin." (PMID 40215345, 2025). "Key components such as genistein, apigenin, kaempferol, chrysin, and luteolin are recognized as active constituents in propolis for diabetes, whilst flavones like naringenin replicate insulin actions and diminish resistance." (PMID 40906303, 2025). "Integrating modern diabetes technologies, such as continuous glucose monitoring, insulin pump therapy, and ketone testing devices, into routine care can also improve metabolic control and help detect early signs of decompensation." (PMID 41149081, 2025). "Emerging therapeutic strategies for diabetes encompass islet transplantation, gene therapy, advanced the insulin analogues and delivery systems, and the hunt for new medicines to prevent and/or stimulate islet β-cell proliferation and regeneration." (PMID 40562805, 2025). "Insulin therapy is the standard treatment for diabetes, with insulin analogs and antihyperglycemic agents becoming increasingly prevalent in treatment compared to human insulin." (PMID 40137145, 2025). "During impaired glucose‐homeostasis states such as diabetes, skeletal muscle can become insulin resistant, resulting in reduced glucose uptake (elevated blood glucose)." (PMID 40985218, 2025). "Conversely, T2D is more common in adults and accounts for approximately 90% of all diabetes cases, characterized by impaired insulin utilization." (PMID 41334449, 2025). "This suggests that insulin therapy, often indicative of more advanced or difficult-to-control diabetes, is a significant correlate of thyroid dysfunction." (PMID 41306154, 2025). "A negative association was observed between insulin therapy use and therapeutic adherence (−0.65; 95% CI −1.20; −0.10), indicating lower adherence in people with diabetes treated with insulin." (PMID 40805882, 2025). "Diabetes is distinguished by chronic hyperglycemia with disturbances in macromolecule metabolism due to impairments in insulin secretion, insulin action, or both." (PMID 40076380, 2025). "Glycaemic control and clinical outcomes in diabetes are improved by continuous subcutaneous insulin infusion (CSII)." (PMID 39496965, 2025). "Histidine supplementation has been found to improve insulin resistance, blood lipid levels and inflammation, and delay the development of atherosclerosis in rodent models of diabetes and metabolic syndrome." (PMID 40438394, 2025). "Biologically, oestrogen protects women from diabetes by improving insulin sensitivity and reducing β-cell death." (PMID 40457495, 2025).
diabetes (continued). "In contrast, factors such as elevated fasting blood glucose, the presence of diabetes-specific complications (e.g., neuropathy), and insulin therapy appear to represent disease-specific amplifiers of depression risk." (PMID 41189617, 2025). "There are many different devices on the market for diabetes management, but this aptamer sensing strategy shows a way to capture important biomarkers, such as insulin resistance, for a quicker diagnosis process." (PMID 40422016, 2025). "This evidence suggests that these formulations mimic the insulin-signaling pathway, making them promising candidates for further investigation in diabetes treatment." (PMID 40014236, 2025). "This topic focused on the use and management of glucose-monitoring devices, such as continuous glucose monitors (CGMs) like Libre sensors, as well as insulin pens, pumps, cannulas, and daily diabetes kits." (PMID 41115270, 2025). "It was authorized by the FDA in June 2014, and it is currently the only inhaled insulin preparation available in the USA for the treatment of postprandial hyperglycemia in adult patients living with diabetes mellitus." (PMID 41012462, 2025). "Our investigation demonstrated that dietary supplementation with inulin effectively attenuated body weight gain, hyperglycemcia, dyslipidmia and insulin levels in murine models of prediabetes and diabetes." (PMID 41264657, 2025). "His past medical history was significant for type 2 diabetes mellitus and diabetic peripheral neuropathy, with long-term insulin use for glycemic control." (PMID 41019039, 2025). "SPINA-GR, an indicator of insulin sensitivity, was significantly lower in the diabetes group (0.61 vs. 1.41 mol/s, p = 0.0057), and SPINA-DI was significantly reduced in the diabetes group (3.29 vs. 5.11, p < 0.0001)." (PMID 40217596, 2025). "Future studies to investigate the effectiveness of different interventions that can improve insulin therapy adherence in Ghana should be undertaken given the increasing burden of diabetes and its complications in the country." (PMID 39854487, 2025). "The objectives of mobile app interventions vary widely, ranging from insulin dose control to improving diabetes knowledge and glucose monitoring through strategies such as text messages, health diaries, and virtual counseling." (PMID 41333527, 2025). "Adaptation includes both adjustment to the daily use of insulin and other aspects of diabetes treatment and also the change in perspective of the person now suffering from a chronic condition." (PMID 40565407, 2025). "Comprehensive diabetes management was commenced, involving subcutaneous injections of Novolog (before meals) and detemir insulin (before bedtime), in conjunction with dietary guidance, exercise education, and blood glucose monitoring." (PMID 41585813, 2025). "Diabetes-related decrease in tissue insulin content was observed only in the duodenum, which also reflects segment-dependent alterations of the muscular environment." (PMID 40497986, 2025). "Saffron‐enriched rye bread can be utilized in diabetes therapy since it increases insulin secretion and lowers triglyceride levels." (PMID 40772023, 2025). "All ‘high-fibrosis’ donors (where diagnosis date was known) had a longer duration of diabetes than ‘high-fat’ donors, and both individuals with insulin-treated diabetes in the overall cohort had highly fibrotic pancreases." (PMID 40991018, 2025). "In diabetes, zinc plays a significant role in the formation of insulin hexameric units, which are the storage forms of insulin in beta cells." (PMID 40869403, 2025). "These programs should cover sick-day management, the importance of insulin therapy and continuity of diabetes care, and understanding early signs of DKA, especially among pediatric cases." (PMID 41375809, 2025). "Diabetes mellitus developed in one patient, who was treated with insulin therapy and had a temporary pause in immunotherapy." (PMID 39859105, 2025).
diabetes (continued). "A systematic review found that diabetes drugs reduce LPS levels, with the strongest effects exerted by thiazolidinediones and the weakest by insulin." (PMID 40278304, 2025). "DKA arises from the progressive β-cell dysfunction in subjects with previously undiagnosed diabetes or from insulin omission, pump failure, or inadequate insulin administration in established diabetes during infections, surgery, trauma, or stress." (PMID 39857941, 2025). "Diabetes mellitus (DM) is a condition consisting of an inability to produce or properly utilize insulin, often resulting in a hyperglycemic status." (PMID 41110543, 2025). "Patients with TVF were more likely to be Chinese, present with STEMI, have more insulin-treated diabetes, reduced left ventricular ejection fraction (LVEF), increased white blood cell count, liver dysfunction, and higher total and LDL-cholesterol at baseline." (PMID 41262724, 2025). "Diabetes mellitus was present in 11 patients (21.5%), of whom 4 (7.8%) were insulin-dependent, 3 (5.9%) were treated with oral antidiabetic drugs (OAD), and 4 (7.8%) were unmedicated." (PMID 41002647, 2025). "High levels of sugar result from inappropriate hormone action—in particular, insulin resistance and decreased insulin secretion from the pancreas are observed in type 2 diabetes mellitus (T2DM)." (PMID 41471783, 2025). "Oxidative stress has been demonstrated in many studies to participate in the progression of diabetes, including mediating an impairment of insulin action increased incidences of complications." (PMID 41244198, 2025). "Throughout this review, we describe how TIM exhibits changes in activity or expression in patients with diabetes, so this new regulation through this enzyme opens the door to understanding why insulin secretion occurs aberrantly in this disease." (PMID 41009376, 2025). "This demonstrates the importance of gene therapy as a promising diabetes treatment method, aiming to restore insulin production, improve β-cell function and modulate glucose metabolism, with numerous preclinical and clinical studies proving its efficacy." (PMID 41226304, 2025). "This novel study has identified a number of experiences and challenges faced by 10 older adults with diabetes managing insulin during surgical admission, as described by the older adults themselves." (PMID 41358572, 2025). "Data were not available to assess the role of resilient facilities in ensuring the continuity of DM health services, e.g., through the continued provision of insulin, access to renal dialysis, and other diabetes-related services." (PMID 40860454, 2025). "Monogenic diabetes can also be diagnosed following a genetic defect of β-cell function or insulin action." (PMID 40943066, 2025). "A study applying circular economy in diabetes products compared reusable versus disposable insulin pens and found that reusable pens reduced plastic waste by approximately 89 percent and carbon emissions by around 40 percent." (PMID 41332366, 2025). "Pioglitazone functions as a specific PPAR‐γ agonist and insulin sensitiser, commonly prescribed for patients with diabetes mellitus or metabolic syndrome." (PMID 40008494, 2025). "In recent decades, advances in diabetes technology have introduced insulin pumps and continuous glucose monitoring (CGM) systems, offering new approaches to disease management." (PMID 41250728, 2025). "Diabetes mellitus, commonly referred to as diabetes, is a chronic metabolic disorder characterized by insulin resistance, where the body is unable to effectively use the insulin it produces, leading to high blood sugar levels, also known as hyperglycemia." (PMID 40385838, 2025). "In the pancreas, LRH-1 promotes β-cell survival and insulin secretion, further linking it to diabetes pathophysiology." (PMID 40926269, 2025). "Diabetes mellitus is a metabolic disorder categorized using hyperglycemia that results from the body’s inability to adequately secrete and respond to insulin." (PMID 40933380, 2025).